KLF2 (KLF transcription factor 2)
Diseases named in the same sentence as KLF2 in open-access papers (continued):
Sharing a sentence is not in itself a finding about the gene and the disease.
Hypertension (4 papers, 2017 to 2022). The presence of chronic increased pressure in the systemic arterial system. "This shows that a decrease in the expression of KLF2 is related to kidney injury caused by hypertension." (PMID 35269384, 2022). "Based on these findings, this study focused on the role of KLF2 in endothelial cell injury caused by hypertension." (PMID 35269384, 2022). "We investigated the role of AT1R and KLF2 in glomerular endothelial damage caused by hypertension." (PMID 35269384, 2022). "In addition, we evaluated the association between KLF2 and glomerular endothelial cell damage caused by hypertension in 5/6 nephrectomy mice and hypertensive nephropathy patients." (PMID 35269384, 2022). "Reduced expression of KLF2 in glomerular endothelial cells due to hypertension was found in both 5/6 nephrectomy mice and patients with hypertensive nephropathy." (PMID 35269384, 2022). "Hypertension-mimicking devices and KLF2 siRNA were used to downregulate KLF2 expression, while the expression of KLF2 was upregulated by administering simvastatin." (PMID 35269384, 2022). "We performed in vitro experiments by applying pressure to hPGECs using a unique hypertension-mimicking machine, and we demonstrated the expression of KLF2, which is reduced by hypertension in mice and humans." (PMID 35269384, 2022). "Here, we demonstrated that KLF2-angiotensin II-AT1R-IL-18 might be an important mediator of apoptosis and fibrosis in the pathophysiology of endothelial cell damage caused by hypertension." (PMID 35269384, 2022). "Further, KLF2 expression in humans is inversely associated with numerous inflammatory and metabolic disease metrics, such as TNFA expression, soluble C-reactive protein levels, body mass index (BMI), and hypertension." (PMID 33208733, 2020). "Here, we investigated the role of KLF2 in hypertensive nephropathy by regulating KLF2 expression in human primary glomerular endothelial cells (hPGECs) and evaluating this expression in the kidney tissues of a 5/6 nephrectomy mouse model as well as patients with hypertension." (PMID 35269384, 2022). "Thus, hypertension appears to contribute to kidney injury and reduce KLF2 expression in vivo." (PMID 35269384, 2022). "Therefore, our results suggest that the linear decrease in KLF2, HPX, TMEM8A, ADAMTS-8 and AP3S2 expression in the broiler kidney is directly or indirectly related to blood pressure, hypertension and weight gain." (PMID 28924246, 2017).
liver cancer (4 papers, 2020 to 2024). An epithelial or non-epithelial malignant neoplasm that arises from the liver. "Although KLF2 acts as a tumor suppressor in several cancers, including GC, reports show that KLF2 acts as an oncogene in liver cancer." (PMID 32075248, 2020). "To analyze KLF2 expression distribution in different cell types in liver cancer and normal tissue, we used Uniform Manifold Approximation and Projection (UMAP) and t-distributed Stochastic Neighbor Embedding (tSNE) algorithm for the single cell expression analysis in multiple platforms." (PMID 37386390, 2023).
acute kidney injury (3 papers, 2021 to 2026). Sudden and sustained deterioration of the kidney function characterized by decreased glomerular filtration rate, increased serum creatinine or oliguria. "This study identifies a molecular mechanism of the O-linked N-acetylglucosamine transferase (OGT)-mediated enhancer of zeste homolog 2 (EZH2)/krüppel-like factor 2 (KLF2)/chemokine (C-X-C motif) ligand 1 (CXCL1) axis underlying the hypercalcemia-induced nerve injury in renal failure." (PMID 34462420, 2021). "In the current study, we explored the regulatory mechanism of OGT in hypercalcemia-induced nerve injury in renal failure and found that OGT promotes this injury by regulating the EZH2/KLF2/CXCL1 axis." (PMID 34462420, 2021). "Taken together, silencing OGT downregulates EZH2, which increases the expression of KLF2 and then decreases the expression of CXCL1, thus alleviating hypercalcemia-induced nerve injury in renal failure." (PMID 34462420, 2021). "Regarding the kidney, recent studies showed that KLF2, KLF4, KLF5, KLF6, and KLF15 were distributed in glomeruli and renal tubules and played important roles in the occurrence and development of proteinuric glomerular diseases and acute kidney injury 28-32,53,54." (PMID 36632460, 2023).
autoimmune disease (3 papers, 2017 to 2021). A disorder resulting from loss of function or tissue destruction of an organ or multiple organs, arising from humoral or cellular immune responses of the individual to their own tissue constituents. "Furthermore, the direct binding of KLF2 to the Foxp3 promoter was observed and Treg-specific deletion of KLF2 using a Foxp3-cre deleter resulted in the onset of autoimmune diseases (Table A1 in Appendix A)." (PMID 34696279, 2021). "As KLF2 is involved in the homeostasis of Tregs, the dysfunction of KLF2 could result in autoimmune diseases." (PMID 34696279, 2021). "Thus, chemicals and drugs, which enhance KLF2 stability would be important for T-regs production and would be helpful in regulation of autoimmune diseases." (PMID 29125549, 2017).
B-cell lymphomas (3 papers, 2022 to 2024). "The usage of this allele is remarkable as it is much less frequent in other types of B-cell lymphomas and is significantly associated with del(7q), KLF2, and NOTCH2 mutations." (PMID 39280243, 2024). "KLF2 mutation is present in 42% of SMZLs, but rarely in other B-cell lymphomas." (PMID 36466816, 2022). "Remarkably, some of these genes (KLF2, TNFAIP3, NOTCH1, HIST1H2BE) are recurrently mutated in HBsAgpos DLBCL and in HCV-associated B-cell NHL." (PMID 39055707, 2024).
cardiomyopathy (3 papers, 2022 to 2025). A disease of the heart muscle or myocardium proper. "KLF2, a regulator identified in our study, has been shown by several studies to inhibit EC growth, proliferation and migration, so it also shows potential as a therapeutic target for the prevention of cardiomyopathy." (PMID 40717095, 2025). "For instance, it is unclear whether KLF2 and KLF4 participate in gestational diabetes mellitus-associated cardiomyopathy." (PMID 38516000, 2024). "Consequently, C6 S100A4+ SMCs may influence cardiomyopathies by promoting EC proliferation and migration through heightened KLF2 expression." (PMID 40717095, 2025).
cavernomas (3 papers, 2020 to 2025). "Inactivation of CCM genes leads to increased endothelial KLF2 expression, a transcription factor important in cavernoma formation." (PMID 39991834, 2025). "Colocalization of Bst1 and the cavernoma transcripts Klf2, Klf4, and Ly6a using Visium showed concentration of Bst1 progenitor cell transcripts at the level of cavernomas and mulberry lesions." (PMID 33138917, 2020). "Inhibition of VEGFR2 does not affect the overexpression of KLF2 or KLF4 after CCM2 loss, but it can partially prevent the development of cavernomas in CCM1-deficient animals." (PMID 33348877, 2020).
clear cell renal cell carcinoma (3 papers, 2024 to 2025). "Finally, in clear cell renal cell carcinoma, KLF2 deficiency inhibits ferroptosis by impairing GPX4 transcriptional repression, promoting tumor migration and invasion." (PMID 38495481, 2024). "KLF2 and GPX4 expression have been found to be negatively correlated, which can cause ferroptosis in renal clear cell carcinoma by regulating GPX4 transcription." (PMID 40969276, 2025).
coronary artery disease (3 papers, 2017 to 2024). "For example, our RNA-seq analyses demonstrated that inhibition of HIF-1α in DF-treated ECs rescued the expression of anti-inflammatory molecules KLF2, KLF4, and PPAP2B (a coronary arterial disease candidate gene identified by genome-wide association studies)." (PMID 28556776, 2017).
Hyperglycemia (3 papers, 2021 to 2022). An increased concentration of glucose in the blood. "In summary, our data show that Azilsartan prevents hyperglycemia-induced hyperpermeability of the BBB by activating the KLF2/occludin signaling pathway." (PMID 34266350, 2021). "Based on these observations, we concluded that Azilsartan protected against hyperglycemia-induced hyperpermeability of BBB via the KLF2/occludin axis." (PMID 34266350, 2021). "Such experiment revealed that inhibition of H3K4me3 catalysis in intermittent hyperglycemia-challenged EC normalized KLF2 level without reversing the level of KLF4." (PMID 35392173, 2022).
lung adenocarcinoma (3 papers, 2021 to 2023). A carcinoma that arises from the lung and is characterized by the presence of malignant glandular epithelial cells. "The obtained data indicated that miR‐126‐5p promoted radiosensitivity of lung adenocarcinoma cells via the EZH2/KLF2/BIRC5 axis while overexpressed BIRC5 reversed the action of miR‐126‐5p." (PMID 35322532, 2022). "Both in vitro and in vivo experiments verified that elevated miR‐126‐5p inhibited cell migration and promoted apoptosis to enhance the sensitivity of lung adenocarcinoma cells to radiotherapy via the EZH2/KLF2/BIRC5 axis." (PMID 35322532, 2022). "RT‐qPCR and immunohistochemical staining exhibited that KLF2 expression decreased in lung adenocarcinoma tissues and cells." (PMID 35322532, 2022). "Data obtained in our study demonstrated that miR‐126‐5p‐mediated EZH2 exerted suppressive effects on proliferation, invasion and inducing effect on lung adenocarcinoma cell radiosensitivity and apoptosis via interaction between KLF2 and BIRC5." (PMID 35322532, 2022). "We then study the effect of miR‐126‐5p regulating the EZH2/KLF2/BIRC5 axis on the radiosensitivity of lung adenocarcinoma cells." (PMID 35322532, 2022). "Collectively, miR‐126‐5p downregulated EZH2 to facilitate the sensitivity of lung adenocarcinoma cells to radiotherapy via KLF2/BIRC5." (PMID 35322532, 2022). "Furthermore, this study also indicated that EZH2 inhibited KLF2 expression to repress the radiosensitivity of lung adenocarcinoma cells." (PMID 35322532, 2022). "Additionally, KLF2 suppressed BIRC5 to promote the radiosensitivity of lung adenocarcinoma cells." (PMID 35322532, 2022). "Therefore, we speculated whether KLF2 played a role in lung adenocarcinoma by regulating BIRC5 expression." (PMID 35322532, 2022). "It was found that KLF2 and BIRC5 were negatively correlated in lung adenocarcinoma through GEPIA2, and BIRC5 was significantly highly expressed in lung adenocarcinoma." (PMID 35322532, 2022). "In the interaction network diagram of 53 genes, 10 genes were at the core position (Degree ≥5), among which KLF2 was obviously downregulated in lung adenocarcinoma tissues, and there was a significant correlation between EZH2 and KLF2 in lung adenocarcinoma." (PMID 35322532, 2022). "Due to the limited known researches, the roles of miR‐126‐5p, EZH2, KLF2, BIRC5 as well as their interaction in the radio‐resistance of lung adenocarcinoma cells should be more clearly investigated." (PMID 35322532, 2022). "The objective of our study was to investigate the effect of miR‐126‐5p, EZH2, KLF2 and BIRC5 in radio‐resistance of lung adenocarcinoma cells and their inner mechanisms." (PMID 35322532, 2022). "miR‐126‐5p and KLF2 were poorly expressed, while EZH2 and BIRC5 were upregulated in lung adenocarcinoma tissues and cells." (PMID 35322532, 2022). "Therefore, it can be concluded that miR‐126‐5p facilitated proliferation, invasion and radiosensitivity of lung adenocarcinoma cells and repressed apoptosis by targeting EZH2 via interaction between KLF2 and BIRC5." (PMID 35322532, 2022).
marginal zone lymphoma (3 papers, 2020 to 2025). A usually indolent mature B-cell lymphoma, arising from the marginal zone of lymphoid tissues. "Along this line, the mutations of KLF2 in humans are involved in the generation of splenic marginal zone B cell lymphomas (SMZBL) (Table A1)." (PMID 34696279, 2021). "Marginal zone lymphomas all share common somatic genetic mutations, including trisomies of chromosomes 3 and 18, deletions at 6q23, and defects in the nuclear factor kappa B (NFkB) and KLF2 pathways." (PMID 40271287, 2025). "In addition, for cases with single BCL6-trans signature, the mutations in several genes were also frequently determined in marginal zone lymphoma, including NOTCH2 (14.6%, 6/41), KLF2 (34.1%, 14/41), TNFAIP3 (19.5%, 8/41), and FAS (17.1%, 7/41) mutations." (PMID 32736575, 2020).
melanoma (3 papers, 2021 to 2026). A malignant, usually aggressive tumor composed of atypical, neoplastic melanocytes. "Similarly, in a melanoma and autoimmune vitiligo setting, LN Tcf-1+ T cells express high levels of Klf2 and Tcf-1- LN effector T cells become TRM." (PMID 36569850, 2022). "Moreover, we were able to show a significant correlation of genes most strongly induced in 3D alginate, with genes induced in malignant melanoma compared to primary melanocytes, including KLF2, KLF4, and EGR1." (PMID 34439267, 2021). "Surprisingly, KLF2 and KLF4 were dispensable for the proliferative and anti-apoptotic effects of compensatory ERK5 activation in MEKi-exposed melanoma." (PMID 41916083, 2026). "In NRAS-mutant melanoma, compensatory ERK5 activation is accompanied by the induction of the Krüppel-like factors KLF2 and KLF4 but their role in MEKi resistance remains unclear." (PMID 41916083, 2026).
multiple sclerosis (3 papers, 2022 to 2025). A progressive autoimmune disorder affecting the central nervous system resulting in demyelination. "Previous studies have revealed that KLF2 deficiency promotes neuroinflammation and alleviates neurological dysfunction in multiple sclerosis mice." (PMID 36632224, 2023). "Hemizygous KLF2+/- mice exhibit, for example, defective macrophage function and abnormal inflammatory responses and myeloid specific KLF2 deficiency exacerbates neuroinflammation in murine multiple sclerosis model." (PMID 36466816, 2022). "Currently, we have used single genes to predict the prognosis of patients and found that both NRAS and KLF2 are good diagnostic genes for multiple sclerosis, and they could independently predict the onset of multiple sclerosis." (PMID 38886317, 2025).
psoriasis (3 papers, 2021 to 2025). An autoimmune condition characterized by red, well-delineated plaques with silvery scales that are usually on the extensor surfaces and scalp. "An in vitro model of psoriasis demonstrated that miR-155-5p acts as a proinflammatory factor by exacerbating inflammatory response via the IRF2BP2/KLF2/NF-κB pathway." (PMID 39934489, 2025). "Regarding BGN, KLF2, and LEPR, the staining properties of epidermal cell nuclei, as well as dermal infiltrating cells and vascular endothelial cells tended to be decreased in both nonlesioned and lesioned areas of patients with AD versus normal and clinical controls (psoriasis)." (PMID 39938773, 2025).
pulmonary fibrosis (3 papers, 2021 to 2025). Chronic progressive interstitial lung disorder characterized by the replacement of the lung tissue by connective tissue, leading to progressive dyspnea, respiratory failure, or right heart failure. "Mechanistically, KLF2 relieves bleomycin-induced pulmonary fibrosis and inflammation by the mediation of Activator protein-1." (PMID 34565285, 2021). "Notably, TH signaling has been shown to inhibit lung fibrosis in mice by improving epithelial mitochondrial function and enhancing alveolar cell differentiation through Kruppel-Like Factor 2 (KLF2) and CCAAT-enhancer binding protein alpha (CEBPA)." (PMID 40605078, 2025). "KLF2 mediates anti-inflammatory and anti-fibrotic effects in pulmonary fibrosis." (PMID 36688692, 2023).
renal carcinoma (3 papers, 2022 to 2024). A carcinoma arising from the epithelium of the renal parenchyma or the renal pelvis. "The distinct metabolic profile of renal cancer is intimately associated with its sensitivity to ferroptosis, with multiple molecular mechanisms implicated in the regulation of ferroptosis in renal cancer, including PDIA4, GPX4, KLF2, ACSL3, and AIM2." (PMID 39092291, 2024).
sarcoma (3 papers, 2022 to 2023). A usually aggressive malignant neoplasm of the soft tissue or bone. "By specifically interfering with KLF2, they demonstrated its importance in the ERK5-mediated effects, highlighting the significance of the ERK5-KLF2 axis as a crucial determinant of sarcoma biology." (PMID 37601096, 2023). "Of note, Klf2 seems to have oncogenic potential in our experimental model, being this report the first connection between this gene and sarcoma biology." (PMID 35884568, 2022). "Moreover, the use of NGS allows us to conclude that ERK5 is a modulator of the transcriptional pattern in sarcoma-derived cell lines induced by 3MC and that its biological activity is mediated through the effect exerted onto KLF2." (PMID 35884568, 2022). "Moreover, we examined the effect of KLF2 dysregulation on patient survival rates and found that only patients with adrenocortical carcinoma (ACC), kidney renal clear cell carcinoma (KIRC), and sarcoma (SARC) had increased survival rates with high KLF2 expression." (PMID 37123417, 2023). "Finally, among the various differentially expressed genes, Klf2 is a key mediator of the biological effects of ERK5 as indicated by its specific interference, demonstrating that the ERK5–KLF2 axis is an important determinant of sarcoma biology that should be further studied in human pathology." (PMID 35884568, 2022).
triple-negative breast carcinoma (3 papers, 2015 to 2023). An invasive breast carcinoma which is negative for expression of estrogen receptor (ER), progesterone receptor (PR), and human epidermal growth factor receptor 2 (HER2). "Hence, by controlling the partitioning of RA between its two transcriptional pathways, KLF2 potently overcame the profound RA-resistance of highly metastatic, triple negative breast cancer cells." (PMID 26416422, 2015).
arteriovenous malformations (2 papers, 2020 to 2024). "In diseases such as arteriovenous malformations (AVMs), Alk1 or ENG (two key genes for AVMs) depletion induced higher-than-normal KLF2/4 expressions, and these increased levels were non-protective." (PMID 32502201, 2020).
asthma (2 papers, 2021). "Asthma patients had neutrophils with a reduced KLF2 expression." (PMID 34696279, 2021). "Thus, reduced amounts of KLF2 in neutrophils promoted the severity of asthma by enhancing neutrophil migration involving CXCR1 and 2 upregulation (Table A1)." (PMID 34696279, 2021). "Importantly, KLF2 was described to have a functional role in asthma." (PMID 34696279, 2021). "Therefore, KLF2 might be useful as a predictive marker of asthma." (PMID 34696279, 2021). "Recently, a study suggested that KLF2, as a regulator of CXCR1/2, may represent an indicator of asthma severity when combined with CXCR1/2." (PMID 33602227, 2021).
bladder cancer (2 papers, 2018 to 2022). "The experiments in vitro suggested that knockdown of ZFAS1 repressed bladder cancer cell proliferation via up-regulating KLF2 and NKD2 expression, and inhibited cell migration and invasion via down-regulating ZEB1 and ZEB2 expression." (PMID 29678899, 2018). "In order to explore the molecular mechanism of ZFAS1 in bladder cancer, we detected the effect of ZFAS1 on the expression of KLF2, NKD2, and EMT-associated genes (ZEB1, E-Cadherin, and Vimentin) by Western blot." (PMID 29678899, 2018). "Thus, knockdown of ZFAS1 repressed bladder cancer cell proliferation via up-regulating KLF2 and NKD2 expression, and inhibited cell migration and invasion via down-regulating ZEB1 and ZEB2 expression." (PMID 29678899, 2018).